ZNF74 (zinc finger protein 74)
Description:
May play a role in RNA metabolism.
Synonyms: ZNF520; Cos52; Zfp520; hZNF7
Tractability: PROTAC: UniProt records ubiquitination sites on it; ubiquitination databases record sites on it.
Gene: Protein-coding gene on chromosome 22 (20,394,115 to 20,408,461, forward strand). Ensembl gene ENSG00000185252.
Subcellular location: Nucleus
Subcellular location (Human Protein Atlas): Nucleoplasm; Actin filaments
Pathways (Reactome):
Gene expression (Transcription): Generic Transcription Pathway
Gene Ontology:
Molecular function: DNA-binding transcription factor activity, RNA polymerase II-specific; RNA polymerase II cis-regulatory region sequence-specific DNA binding
Biological process: regulation of DNA-templated transcription; regulation of transcription by RNA polymerase II
Cellular component: nucleoplasm; nucleus
Genetic constraint (gnomAD): Loss-of-function variants: 11 observed, 15.38 expected, observed/expected ratio (o/e) 0.72, 90% interval 0.45 to 1.18. The upper end of that interval is the gene's LOEUF score, 1.18, which puts it in group 5 of 6, group 1 being the genes least tolerant of losing a copy. Missense variants: 806 observed, 903.11 expected, observed/expected ratio (o/e) 0.89, 90% interval 0.84 to 0.95. Synonymous variants: 354 observed, 379.13 expected, observed/expected ratio (o/e) 0.93, 90% interval 0.86 to 1.02.
Homologues: Orthologues: chimpanzee ZNF74 (99% identical), macaque ZNF74 (97% identical), rabbit ZNF74 (74% identical), pig ZNF74 (61% identical). Paralogues in human: ZNF568 (38% identical), ZNF7 (38% identical), ZNF235 (37% identical), ZNF28 (37% identical), ZNF724 (37% identical), ZNF726 (37% identical), ZNF841 (37% identical), ZNF595 (37% identical), ZNF454 (37% identical), ZNF728 (37% identical), ZNF879 (37% identical), ZFP28 (36% identical), and 164 more.
Diseases named in the same sentence as ZNF74 in open-access papers:
ZNF74 is named in the same sentence as 3 diseases in open-access papers, as found by Europe PMC text mining. Sharing a sentence is not in itself a finding about the gene and the disease. The quoted sentences say what the papers report.
schizophrenia (2 papers, 2008 to 2020). A major psychotic disorder characterized by abnormalities in the perception or expression of reality. "ZNF74 was identified as a candidate gene for modifying the development of schizophrenia in particular patient groups." (PMID 32117005, 2020). "In the same direction association studies have reported several genes of this region associated with risk to develop schizophrenia and bipolar disorder, including PRODH, COMT, ZNF74, PCQAP, UFD1L, ZDHHC8, DGCR2 and SNAP29." (PMID 18284679, 2008). "ZNF74 encodes a KRAB-ZNF, is highly expressed in the developing brain and is located on chromosome 22q11, a gene segment previously identified as a positional candidate locus for the susceptibility to schizophrenia as part of the 22q11 deletion syndrome." (PMID 32117005, 2020). "Several polymorphisms identified in ZNF74 are significantly associated with age-at-onset of schizophrenia, although no statistical difference was detected for their frequencies between the patients and control subjects." (PMID 32117005, 2020).
congenital heart disease (1 paper, 2024). A heart disease that is present at birth. "ZNF74 is an important coding gene for the formation of RNA-binding protein tightly associated with the nuclear matrix, which has been reported to have a significant association with cardiac defects such as congenital heart disease." (PMID 38927450, 2024).
ZNF74 also shares sentences with these, for which no sentence is quoted: bipolar disorder (1 paper).